IRF7 (interferon regulatory factor 7)
Diseases named in the same sentence as IRF7 in open-access papers (continued):
Sharing a sentence is not in itself a finding about the gene and the disease.
infection (continued). "The results showed that the expression levels of TLR3, IRF7, IFN-α/β and the corresponding downstream antiviral factors OAS, PKR and Mx were all upregulated in the SPF chicken ILP cells at 8 h post-infection (hpi) and 12 hpi." (PMID 35215986, 2022). "Compared to mock infection, U937 cells infected with control HIV-1 increased the levels of phosphorylation of IRF3 and IRF7 1.6- and 1.8-fold at 4 hpi, respectively." (PMID 33690734, 2021). "Regulation of IRF7 expression and function is utilized by α- and γ-herpesviruses as a means to dampen the IFN response during infection." (PMID 34411201, 2021). "To test these possibilities, we knocked down either IRF3, IRF7, or both with specific siRNA pools prior to SFSV and clone 13 infection." (PMID 34726591, 2021). "Analysis of the IFN-stimulated genes (ISGs) Ifitm3, Irf7, Isg15, and Oas1a at 12, 24, and 72 hpi demonstrated a consistent trend for increased expression following ZIKVCDN infection." (PMID 34193875, 2021). "IFN-I also activates IRF7, particularly in pDCs; IRF3 is essential for upregulation of IFN-I genes during the early stages of infection and for potentiating the overall IFN-I response via positive-feedback with IRF7." (PMID 34917078, 2021). "For example, IRF7 overexpression inhibited SGIV replication, and ISG15 was able to decrease RGNNV infection in grouper cells." (PMID 33767703, 2021). "The modules that were co-up-regulated in CD4 and CD8 cells after infection included IRF9, IRF7, PLCB3, CXCL3, and TXN, among others." (PMID 34603402, 2021). "These genes’ expressions were decreased on day 33; however, compared with mock infection, IFNα, Rig-I, OAS-1, IRF7, MxA, and IL6 were also expressed at a statistically significant higher level." (PMID 32121148, 2020). "As shown by dual-luciferase assay, various degrees of decreased promoter activities of RLR signaling pathway key molecules, including RIG-I, IPS-1, STING, TBK1, and IRF7, were detected after VP4 overexpression under GCRV infection or when uninfected." (PMID 32268551, 2020). "SARS-CoV infection induces NF-κB targeted genes, like IL-6 and IL-8, early in the infection, while IFN-I induction by IRF3 and IRF7 is delayed until 48 h after infection." (PMID 33377937, 2020). "In reverse, EVA71 infection down-regulates TLR7 and its downstream products in 16HBE cells, including MYD88, interferon regulatory factor 7 (IRF7), and the secretion of type I IFN, markers for activation of innate immune responses." (PMID 33298183, 2020). "IFNα, IFNβ, IFNλ1, Rig-I, IRF3, IRF7, OAS-1, MxA, IL6, IL8, and TNFα expressions were increased at either day 1 or day 2 in HFDPCs post-infection or on both days." (PMID 32121148, 2020). "To understand the antiviral response in the CHME3 human microglial cell line, we next investigated the expression levels of antiviral genes MDA5, RIG-I, MX1, IRF7, IFNβ, and ISG15 following infection with PRVABC59 ZIKV." (PMID 32373079, 2020). "In the present study, we tested the effect of ncpBVDV infection and IFNT challenge on the expression of IRF7 and IRF9 mRNA." (PMID 31861316, 2019). "Infection of a single (IRF3−/− and IRF7−/−) and double (IRF3/7−/−) knockout mice clearly demonstrates that either IRF3 or IRF7 is required for survival following CHIKV infection, with IRF3/7−/− mice showing significant viral dissemination with high titres." (PMID 30909385, 2019). "Infection of RNA viruses or their production of RNA intermediates can activate a subset of ISGs through activation of IRF3, IRF7 and NF-κB." (PMID 30952992, 2019). "Infection of wild-type and interferon-defective IRF3-/--IRF7-/- or IFNAR-/- mice with sfRNA defective WNV strains demonstrated that sfRNA production is critical to sustain infection in animals with intact interferon response." (PMID 30646609, 2019).
infection (continued). "We found that the expression levels of IRF-7, IFIT1, IFIT2, and RIG-I showed statistically significant differences after infection with hNS1-expressing recombinant viruses or aNS1-expressing recombinant viruses at certain time points." (PMID 31597767, 2019). "It has been reported that the difference in rNDV infectivity between tumor cells and normal cells is responsive to IFN-β, the gene expression of RIG-I, IRF-3, IRF-7, and IFN-β before infection or the RIG-I gene and the receptor of type I IFN expression." (PMID 29882780, 2018). "Next, we compared the host responses against H6N2 infection between the cell lines (Control/Mock vs. Control/H6N2 and Cuo-IRF7/Mock vs. Cuo-IRF7/ H6N2) to investigate which genes and pathways were potentially modulated by IRF7 upon infection." (PMID 30356848, 2018). "Infection with either strain increased expression of ISGs (GBP1, IFIT1, IRF7) and reduced expression of lymphocyte related genes (CD3D, CD8A, ZAP70)." (PMID 28852031, 2017). "In contrast, CCR2-DTR → Irf3-/-;Irf7-/- mice treated with PBS were protected against severe RRV disease, indicating that IRF3 and IRF7 sufficient hematopoietic cells can protect Irf3-/-;Irf7-/- mice against RRV-T48-nsP16M infection." (PMID 29244871, 2017). "Taken together, our data indicate that infection of GM-BM with ECTV inhibits nuclear translocation and sustained retention of NF-κB/p65, IRF3 and IRF7 in the nucleus induced by LPS treatment." (PMID 28604814, 2017). "Meanwhile, the expression of both DDX58 and IRF7, the master transcription factor for type I IFN, were upregulated at both 6 and 16 h of infection." (PMID 28993767, 2017). "The role of IRF7 in the regulation of Nod-like receptor signaling and oxidative stress pathways during HRV infections merits further investigation in follow-up studies." (PMID 26810609, 2016). "Disrupting the expression of PRR, IPS-1, IRF3, IRF7 and suppressing NF-κB significantly inhibited the production of IFN-β, IL-28A/B and IL-29 in the host following ATMUV infection." (PMID 27449021, 2016). "Infection mildly increased nuclear IRF7 expression and a further increase was observed in MDP-pretreated HCMV-infected cells, suggesting that MDP triggered IRF7 localization and possible activation in the nuclear fraction of infected cells." (PMID 26830977, 2016). "Transcription factor IRF7-dependent amplification of type I and III IFNs is required for protection against primary infection by IAV in humans." (PMID 27604339, 2016). "After infection with 2x105 Focus Forming Unit (FFU) PR8M virus, Irf7−/− mice lost significantly more body weight and exhibited increased mortality compared to wild type controls." (PMID 26329040, 2015). "After 8 days of intra-peritoneal injection of TORISEL (10mg/kg, injected every 2 days), irf3-/-/ irf7-/-mice were infected by CHIKV and tissues were analyzed at day 1 and 2 post-infection." (PMID 26317997, 2015). "Enhanced anti-viral responses and IRF7 down-regulation of RelA expression likely results in decreased HIV-1 replication and improved TFV’s efficacy specifically early during infection and in the presence of suboptimal TFV concentrations." (PMID 26121689, 2015). "Therefore, since TLR3 and TLR4 molecules contribute to the generation of a normal IFN response through activation of IRF-3, IRF-5, and IRF-7 after infection with neurotrophic virus, we tested whether the ablation of TLR3 and TLR4 molecules affected type I innate responses in JEV infection." (PMID 25188232, 2014). "The mRNA levels of IRF-7 and IFN-α1, a target gene product of IRF-7, were transiently increased and reached peaks 6 hrs post-infection (p.i.)in both PHH and HuS-E/2 cells (closed and open circles)." (PMID 24587086, 2014). "This has been observed during the response of mice to infection with vaccinia virus, where a subset of Ly6Chi inflammatory monocytes produces type I IFN in an IRF3 and IRF7-dependent manner after TLR2-mediated recognition of viral ligands." (PMID 22815909, 2012).
infection (continued). "Expression of IRF7 in HEK293 cells led to the induction of the IFNα4 promoter linked to a luciferase reporter gene, which was further increased by infection with Sendai virus (SV), a ssRNA virus known to induce the RIG-I-IRF7 signaling pathway." (PMID 22046272, 2011). "Cells were sorted and infected with Ad5/3-Delta24 and four and 24 hours following infection, mRNA was collected and analyzed for type I interferons (IFNα and IFNβ) interferon regulatory factors IRF3, IRF7 and transcription factor STAT1 expression." (PMID 21079774, 2010). "We detected very high expression levels of Irf7 in both DA and PVG rats within the first 24 hours after infection." (PMID 20806060, 2010). "In this study, using a mouse model of WNV infection, we evaluate the combined role of two key transcription factors, interferon-regulatory factor-3 (IRF-3) and IRF-7, that orchestrate antiviral and interferon (IFN) responses after infection." (PMID 19798431, 2009). "In blood, plasmacytoid DC (pDC) are believed to be primary producers of type I IFN during infection by RNA viruses; in pDC, IFN is induced after nucleic acid recognition by TLR7 and signaling through MyD88 to IRF-7." (PMID 19798431, 2009). "The higher resistance of PANC-1 cells to 17D infection, compared to MIA PaCa-2 cells, may be attributed to the increased expression of IRF2 and IRF7, which regulate the interferon α and γ genes in this cell line." (PMID 39852819, 2025). "Similarly, HW infection suppresses select type I interferon-related genes (TAP1 and IRF7) in the intestine, but this effect is reversed by CoV coinfection, suggesting a shared IFN-driven antiviral mechanism." (PMID 41268552, 2025). "At 24 h post-infection, HMPV boosted ISG15, OAS1, MX1, and IRF7 by multiples of ten magnitudes." (PMID 40732740, 2025). "We found that, in addition to a broad induction of ISGs (for example, DTX3L, OAS3, RTP4, IRF7, MX2, IFIT3, IFIH1), only IFNB1 and, more robustly, IFNL1-like and IFNL3-like were induced in virus-infected organoids at 1 and 3 days after infection compared to the uninfected controls." (PMID 40399606, 2025). "By 72 h post-infection, although only five common genes (IFI44, OASL, OAS3, IRF9, IRF7) are identified, these genes contribute significantly to a range of crucial GO processes, emphasizing the depth of the immune response despite the limited number of genes involved." (PMID 38957806, 2024). "Moreover, the involvement of the “type I interferon signaling pathway” with genes like IRF7 and STAT2 highlights the role of interferon responses in modulating the immune landscape during the later stages of infection." (PMID 38957806, 2024). "Likewise, the most abundant group of upregulated genes after infection with swH1N1 was ISGs or genes involved in their activation (DDX58 (RIG-I), ZBP1, IFIH1 (MDA5), IRF7, and DDX60)." (PMID 39247193, 2024). "We also noticed that IRF7 and ISG20 expression fell slightly below baseline near 28 days postsymptom-onset, suggesting potential downregulation of these genes at later stages of infection." (PMID 38580667, 2024). "Knockout of IRF7 in mice leads to a slight increase in LGTV RNA in the brain following peripheral infection but does not influence disease onset or mortality." (PMID 39205301, 2024). "After infection, the expression of MAVS, IRF7, STING, NF-κB, MAD5, LGP2, IFN-α and IFN-β was upregulated compared with that in the control group, regardless of whether IFITM3 was overexpressed or inhibited." (PMID 38543696, 2024). "As we observed that the protein levels of IRF7 were significantly reduced during the later stages of infection (≥18 hpi), regardless of the IBDV titer." (PMID 39872942, 2024). "On average, mice that succumbed to infection (either JEVNakayama, JEVFU, JEVNSW/22 or MVEVTC123130) had a more robust viremia, further implicating a higher viremia in a higher chance of lethal neuropenetrance in Irf7−/− mice." (PMID 40295675, 2024).
infection (continued). "IRF3, unlike IFR7, is degraded rapidly after infection without being newly reproduced, and like IRF7, the lack of IRF3 can negatively affect the immune response due to the lack of induction of IFN-α/β." (PMID 38932312, 2024). "CAV21 infection of mock-treated cells led to blunted p-STAT1(Y701) without downstream IRF7 induction or type-I IFN release." (PMID 37962360, 2023). "IRF7 induction has been noted in SNV infection of HLMVECs and during infection of Syrian golden hamsters where there was a similar lack of IRF3 induction with upregulation of IRF7." (PMID 37766212, 2023). "In spleens significant differences in viral load were detectable on 2 and 4 days post-infection in Irf7−/− mice when compared to WT animals, further no viral RNA was detectable from day 7 post-infection." (PMID 37737190, 2023). "The inability to produce IFN-I was independent of the infection rate since Irf7−/− pDCs, mDCs and macrophages showed similar infection rates upon challenge with LGTV (data not shown)." (PMID 37737190, 2023). "Infection of both viruses efficiently induced ISGs and activated IRF1, IRF3 and IRF7, suggesting that the antiviral innate response of infected cells is not fully suppressed during infection." (PMID 37197656, 2023). "Furthermore, the temporal expression profiles of eight selected antiviral-related mRNA including IRF3, IRF7, IKKβ, TBK1, IFIT1, IFI44, MX1 and ISG15 were detected by qRT-PCR, which showed a significantly stronger response at early infection under 20 °C." (PMID 37627029, 2023). "TLR and RIG-I/MDA-5 signaling mediate the SUMOylation of IRF7 but not the IFN-activated JAK/STAT pathway in response to vesicular stomatitis virus (VSV) or encephalomyocarditis virus (EMCV) infection." (PMID 37638030, 2023). "In our study, the wtHB-E326KNS3519T infection significantly upregulated the expression of RIG-I compared with the smHB-E326ENS3519T group, which further stimulated the transcription of a large amount of IRF7 and type-I IFN." (PMID 38140617, 2023). "Interestingly, IRF7 was shown to impair early splenic CD4+ Th1 cell activation, thereby promoting infection by blood-stage Plasmodium." (PMID 37251373, 2023). "Inborn errors of IRF7- and TLR3-dependent type I IFN immunity cause life-threatening COVID-19 pneumonia in patients without prior severe infection." (PMID 37006316, 2023). "Surprisingly, similar to WT mice Irf3−/− and Irf7−/− animals survived the infection with no obvious signs of disease." (PMID 37737190, 2023). "The authors found that recruitment of IRF7 to phagosomes was specific to infection with Leishmania, as it did not occur when latex beads were internalized by macrophages that had been pre-treated with Poly I:C." (PMID 35154115, 2022). "Interestingly, OROV-infected IFN regulatory factor 5 KO (IRF5−/−) mice exhibited signs of hepatic injury early in the infection, increased viral titers in the spinal cord, and delayed death relative to IRF3−/− IRF7−/− DKO mice." (PMID 35301331, 2022). "Total amount of IFR3 was not affected, whereas IRF7 was increased following H. pylori J99 infection." (PMID 36317079, 2022). "Moreover, infection led to an upregulation of IFN signaling pathway-related genes and to the induction of Isg15 and Irf7." (PMID 35215832, 2022). "Infection can trigger various pathogen recognition receptor (PRR) signaling pathways, which converge on TBK1-mediated phosphorylation and activation of the IRF3 and IRF7 transcription factors." (PMID 35244540, 2022). "In conclusion, infection with the NIBV SX9 strain activates the TLR7 signaling axis in target tissue, activates the nuclear transcription factors IRF7 and NF-κB, induces the production of proinflammatory cytokines, causes an inflammatory response and leads to kidney damage." (PMID 35402297, 2022). "This may explain the observation in this study that expression of IRF7 in KO IFNAR1 cells promotes the expression of IFIT5 and IRF1 at the later stage of infection." (PMID 35891486, 2022).
infection (continued). "In this study, IRF7 and MX1 were upregulated in coinfected cells, which indicated that MDV and REV coinfection in CEF cells leads to pronounced induction of innate immune responses in comparison to a single infection." (PMID 35392111, 2022). "We also found recruitment of IRF7 to parasite-containing phagosomes early on in infected macrophages of C57BL/6 mice, which was maintained at 24 h, showing similarities between the infection of those two L. donovani strains, LV9 and MW897, in different macrophage populations." (PMID 35154115, 2022). "IRF7 and IRF9 are upregulated in SARS-CoV-2 infection and severe viral load may overwhelm the IFN response and determine the outcome of the infection." (PMID 36091053, 2022). "Irf7, a key gene involved in the regulation of IFNα was strongly upregulated (5.3 log2) at day 5 post-infection (p=2,71x10-281) but none of the IFNα genes were." (PMID 35812400, 2022). "Other experiments have shown that IRF7 and IRF9 are upregulated in SARS-CoV-2 infection and that severe viral load may overwhelm the IFN response and determine the outcome of the infection, manifesting as a dysregulated IFN response." (PMID 36091053, 2022). "Induction of the IFN I pathway after infection with the wt isolate was evident by up-regulation of several interferon-induced proteins, i.e., IFIT-I, ISG15, IFI44, GIG1, interferon-induced very large GTPase 1, IRF3, IRF7, and Mx." (PMID 35215144, 2022). "Finally, ROC curve analysis demonstrated that IL-27 (p < 0.001 and AUC = 0.956) and IRF7 (p < 0.001 and AUC = 0.982) might be more important candidate for further studies in the field of finding probable biomarkers for filtering BK active infection from inactive ones." (PMID 34996392, 2022). "Upon infection, this cluster enriched a strong interferon-stimulated gene (ISG) signature, including master antiviral regulators Irf7, Oas3, and Isg15, suggesting induction of the ISG program could occur in neutrophils under severe conditions." (PMID 35420442, 2022). "Furthermore, a gradual up-regulation of IRF7, IRF9, STAT1 and STAT2 genes was observed in Calu-3 cells after the infection with SARS-CoV-2 for 24 h." (PMID 34578229, 2021). "We also examined the effect on OM-85 on the expression of selected IRF7 pathway genes in whole lung, and although the findings were mostly not significant, there was a trend for stronger effects of OM-85 in BN compared to PVG particular at D2 post infection." (PMID 34367159, 2021). "Our results showed that IRF7 specifically mediated the infection-induced MHC class I upregulation which was not recognized previously." (PMID 34389779, 2021). "Upon infection with RNA viruses, TBK1 is activated by the upstream protein MAVS, and activated TBK1 recruits IRF3 and IRF7; these proteins undergo TBK1-mediated C-terminal phosphorylation to trigger their dimerization and nuclear translocation, an event followed by induction of IFN secretion." (PMID 34782737, 2021). "p62 knockdown significantly reduced levels of IRF7, ISG15, IFIT1, IFIT2, and IFIT3 genes, suggesting that p62 was required for maximal activation of the innate immune response during KSHV primary infection." (PMID 33414399, 2021). "At the transcriptome level, the high expression levels of viral sensors MDA5 (IFIH1), R1G-1 (DDX58), and ISGS (ISG15, Mx1, Mx2, RSAD2, IFIT3, and IFIT5) and transcription factors like IRF-7 and STAT-1 that induce ISG expression were found in lymphocytes during virulent PPRV infection." (PMID 34631844, 2021). "Unlike IRF3, IRF7 is not expressed ubiquitously in cells; instead, its expression is induced upon pathogen infection or stimulation." (PMID 34782737, 2021). "Differential gene-expression analysis indicated that 180 genes were significantly upregulated, and 164 genes were significantly downregulated in IRF7-/- cells compared to their expressions in IRF7wt cells without infection (FDR < 5%)." (PMID 32252379, 2020).